EGR1 (early growth response 1)
Diseases named in the same sentence as EGR1 in open-access papers (continued):
Sharing a sentence is not in itself a finding about the gene and the disease.
cardiomyopathy (5 papers, 2014 to 2025). A disease of the heart muscle or myocardium proper. "Upregulated DEGs were associated with pro-fibrotic signaling, such as TGF-β signaling-associated genes (TGFB1, LTBP1, ANKRD1) and other cardiomyopathy-related signaling, such as the MAPK cascade (ADRA1A, EGR1, IL6R)." (PMID 37084237, 2023). "Re-analysis of the 22 TFs and differential expressed genes (DEGs; 143 up-regulation and 136 down-regulation) from the cardiomyopathy-related Gene Expression Omnibus (GEO) dataset GSE57338 revealed early growth response 1 (EGR1) as the only overlapping molecule." (PMID 40822127, 2025). "Egr-1 also plays a role in doxorubicin-induced cardiomyopathy." (PMID 37057102, 2023). "In silico analysis showed several of these piRNAs were computationally predicted to target and potentially regulate expression of genes including SMAD2, EGR1, ICAM1, CX3CL1, and CXCR2, which have been implicated in parasite infection, pathogenesis, and various cardiomyopathies." (PMID 36936778, 2023). "Therefore, different mitochondrial stress factors could activate the nuclear transcription factor, EGR1, via ANT1 overexpression, which further increased the mPOS-related cell-killing mechanism, thereby causing cardiomyopathy." (PMID 37057102, 2023).
chronic obstructive pulmonary disease (5 papers, 2008 to 2025). A chronic and progressive lung disorder characterized by the loss of elasticity of the bronchial tree and the air sacs, destruction of the air sacs wall, thickening of the bronchial wall, and mucous accumulation in the bronchial tree. "Additionally, it was reported that LC3B was regulated by the transcription factor Egr-1 in cigarette smoke-induced chronic obstructive pulmonary disease." (PMID 29545906, 2018). "Compounds found in cigarette smoke can induce EGR1 expression through airway hyperresponsiveness (AHR), which subsequently leads to bronchial epithelial cell apoptosis and chronic obstructive pulmonary disease (COPD)." (PMID 40811488, 2025). "Increasing studies demonstrated Egr-1 played an important role in many inflammation and fibrosis diseases, and highly expressed in the lungs of smokers with chronic obstructive pulmonary diseases (COPD)." (PMID 23874821, 2013).
clear cell renal cell carcinoma (5 papers, 2012 to 2023). "Bioinformatics assessment revealed a correlation between p300, EGR1 and MAML1 copy number and mRNA alterations in renal clear cell carcinoma and p300, EGR1 and MAML1 gene alterations were associated with increased overall survival." (PMID 23029358, 2012). "Overexpressed miR-125b-2-3p notably increased lymphatic invasion and distant migration by targeting EGR1 in clear cell renal cell carcinoma." (PMID 34178038, 2021).
endometriosis (5 papers, 2020 to 2023). The growth of functional endometrial tissue in anatomic sites outside the uterine body. "Another study with peritoneal fluid from women with endometriosis showed that TNFA signaling could increase EGR1 expression and collaborate with establishing and maintaining the disease." (PMID 36232817, 2022). "Repeated genes from the MS-phase (CCN1, CRISP3, EGR1, FOS, FOSB, and TRPM6) could be associated with affected receptivity in endometriosis." (PMID 32474803, 2020).
esophageal squamous cell carcinoma (5 papers, 2021 to 2023). Esophageal squamous cell carcinoma (ESCC) is a type of esophageal carcinoma (EC) that can affect any part of the esophagus, but is usually located in the upper or middle third. "The EGR1 mRNA underwent m6A modifications through the action of METTL3, and YTHDF3 enhanced its RNA stability to upregulate the EGR1/Snail signaling pathway and support cancer metastasis in esophageal squamous cell carcinoma." (PMID 37012388, 2023). "In esophageal squamous cell carcinoma, EGR1 is the key transcriptional activator of LCN2 within a positive LCN2-MEK/ERK-LCN2 loop to promote the migration and invasion of esophageal squamous cell carcinoma cells." (PMID 35817941, 2022). "In esophageal squamous cell carcinoma, LCN2 expression is modulated by the transcription factors TCF7L2 and EGR1, leading to increased activity of matrix metalloproteinase-9 (MMP-9), rearrangement of cytoskeletal F-actin, as well as increased invasiveness and migration through the MEK/ERK pathway." (PMID 34062746, 2021). "For example, METTL3 promotes the development of esophageal squamous cell carcinoma (ESCC) through the stabilization of NOTCH1 and EGR1 mRNA, followed by activation of Notch and EGR1/Snail signaling pathways." (PMID 37965577, 2023).
lung disease (5 papers, 2017 to 2025). "Increased expression of EGR1 was found to be significantly associated with mild lung disease (fold change = 4.5; FDR P = 3.1x10-6)." (PMID 28846703, 2017). "Elevation in the expression of the EGR1 gene was previously reported in pulmonary diseases and bacterial infections, including P. aeruginosa." (PMID 35508983, 2022). "Analysis of Egr1 revealed upstream control by SRF, ELK1, and CREB, all of which are involved in activity-dependent gene expression, lung disease and response to infection." (PMID 40831503, 2025). "EGR1 can stimulate collagen synthesis and induce autophagy-related LC3B expression in pulmonary disease." (PMID 37958504, 2023). "In addition, EGR1 not only enhances renal collagen transcription, but it was also reported to induce autophagy-related LC3B expression in pulmonary disease." (PMID 37958504, 2023).
Myocardial fibrosis (5 papers, 2022 to 2024). "At the same time, EGR1 knockdown retarded myocardial fibrosis while silencing miR-150-5p exacerbated fibrotic expansion, as evidenced by H&E and Masson’s trichrome staining." (PMID 36140279, 2022). "In contrast, another known fibrosis regulator, namely, early growth response 1 (EGR1), was found to improve cell proliferation and enhance the expression of three fibrosis-related proteins, MMP-13, collagen I, and collagen III, in the myocardial fibrosis cell culture." (PMID 36140279, 2022).
osteoporosis (5 papers, 2022 to 2025). A condition of reduced bone mass, with decreased cortical thickness and a decrease in the number and size of the trabeculae of cancellous bone (but normal chemical composition), resulting in increased fracture incidence. "Furthermore, early growth response 1 (EGR1), a transcription factor of METTL3, can promote osteoclast differentiation and osteoporosis development by regulating the METTL3/m6A/Chi3l1 axis." (PMID 39769202, 2024).
stomach cancer (5 papers, 2010 to 2024). "The expression of EGR1 is significantly higher in a primary gastric tumor and metastases than in normal gastric tissues, and EGR1 expression correlates with tumor size, depth of invasion, tumor stage, and prognosis." (PMID 33842351, 2021). "Constitutive Egr-1 expression has been shown to correlate with prostate and gastric tumour aggressiveness and metastasis." (PMID 20087343, 2010).
triple-negative breast carcinoma (5 papers, 2018 to 2023). An invasive breast carcinoma which is negative for expression of estrogen receptor (ER), progesterone receptor (PR), and human epidermal growth factor receptor 2 (HER2). "The expression level of EGR1/4 in the triple-negative breast cancer (TNBC) group decreased (p < 0.0001)." (PMID 31844579, 2019). "Our study aimed to investigate the role of Early Growth Response 1 (EGR1) in regulating VM in aggressive cancer cells, specifically MDA-MB-231 triple-negative breast cancer cells." (PMID 37762678, 2023). "In triple negative breast cancers (TNBCs), the Y-box binding protein (YB-1) promotes paclitaxel (PTX) resistance by reducing EGR1 levels and cells with lower levels of EGR1 were more resistant to PTX." (PMID 29719592, 2018).
atopic dermatitis (4 papers, 2022 to 2025). "For example, increased Artn and EGR1 levels in atopic dermatitis correlate with enhanced nerve density and scratching, both of which are attenuated in EGR1-deficient mice." (PMID 39229121, 2025). "In keratinocytes, BCP specifically counteracts Th2-driven inflammation by suppressing the IL-4/IL-13–MAPK–early growth response 1 (EGR1) axis, which otherwise promotes thymic stromal lymphopoietin (TSLP), a central epithelial alarmin in atopic dermatitis." (PMID 41304852, 2025).
Chronic Myelogenous Leukemia (4 papers, 2017 to 2022). "Our data provide an important extension of this notion, showing for the first time that loss of Egr1 accelerates BCR-ABL driven chronic myelogenous leukemia." (PMID 29050203, 2017). "This large body of evidence consistent with Egr1 behaving as a tumor suppressor in hematopoietic cells, both in vivo & in vitro and in both humans and mice, led us to ask if Egr1 plays a role in Chronic Myelogenous Leukemia (CML)." (PMID 29050203, 2017). "Tumor suppressor activity of EGR1 is well proven in Chronic Myelogenous Leukemia (CML) as well." (PMID 35923847, 2022). "In conclusion, the results obtained indicate that Egr1 is a critical tumor suppressor of BCR-ABL driven chronic myelogenous leukemia providing the impetus to further investigate the role of Egr1 and explore its potential as a therapeutic target in other cancers." (PMID 29050203, 2017).
cognitive decline (4 papers, 2015 to 2025). "More recently, EGR1 has also been implicated as a driving factor of AD neuropathology and cognitive decline, since hippocampal EGR1 inhibition was shown to reduce tau phosphorylation, lower Aβ pathology, and improve cognition in 3xTG-AD mice." (PMID 30227888, 2018). "Thus, high-intensity interval training appears to counteract cognitive decline by reinstating a coordinated gene network with Arc and Egr1 to initiate synaptic transcriptional programs and Adcy1 to restore intracellular signaling, culminating in improved memory-related neural plasticity." (PMID 41516177, 2025). "The markers related to cognitive decline were classified into the following two groups: Neuroinflammatory markers: IL-1β, IL-6, tumor necrosis factor-α (TNF-α) and genetic markers (Bdnf, Arc, Egr1) which were estimated in brain regions." (PMID 33918576, 2021). "The effects of EGR1 may counteract Aβ-mediated synaptotoxicity; in patients who show AD pathology but do not have cognitive decline (Braak stages II–III), EGR1 may be upregulated to increase synaptic plasticity as an attempt to compensate for Aβ-induced neuropathology." (PMID 30227888, 2018).
cyst (4 papers, 2019 to 2025). A sac-like closed membranous structure that may be empty or contain fluid or amorphous material. "Pharmacological inhibition of EGR1 retarded cyst enlargement in in vitro, ex vivo, and in vivo ADPKD models." (PMID 41810077, 2025). "Disruption of EGR1 phase separation significantly alleviated cyst growth in the forskolin-induced 3D spheroid model of mIMCD3 cells and MDCK cyst model." (PMID 41810077, 2025). "Examination of puc-lacZ showed comparable LacZ expression in cyst cells between egr1 and heterozygous controls." (PMID 31295251, 2019). "Moreover, Egr1 can be downregulated by curcumin, a compound able to reduce cyst formation in vivo." (PMID 31773180, 2019). "This study utilized in vitro cell models, three-dimensional (3D) cyst model, embryonic renal cystic model, and PKD mouse model to clarify the role of EGR1 in cyst development of ADPKD." (PMID 41810077, 2025).
dementia (4 papers, 2019 to 2022). Loss of intellectual abilities interfering with an individual's social and occupational functions. "In dementia rat models, tFUS-induced BBB disruption in the hippocampus increased brain-derived neurotrophic factor (BDNF), early growth response protein 1 (EGR1), and hippocampal neurogenesis, which lead to improved spatial memory." (PMID 35207738, 2022).
endometrial cancer (4 papers, 2021 to 2024). Primary or metastatic malignant neoplasm involving the endometrium (mucous membrane that lines the endometrial cavity). "Our results are also consistent with previous studies assessing the level of EGR1 in endometrial cancer cells." (PMID 34768392, 2021). "Indeed, ChIP‐seq signal for the EGR1 protein in cultured cell lines (ECC1: endometrial cancer; K562: erythromyeloblastoid leukemia) overlapped that of the LDB2 protein in neurosphere cells at the promoter region of ARC." (PMID 33656268, 2021). "Excessive expression of the H1–H3 receptors and the EGR1, as well as the silencing of the H4 receptor and calmodulin, may suggest their potential relationship with endometrial cancer progression." (PMID 34768392, 2021). "The expression of Egr-1 in breast and endometrial cancer cells is stimulated by E2 and hydroxytamoxifen (OHT) and mediated via GPER/EGFR/ERK signaling and in model cell lines (breast and endometrial cancer cells)." (PMID 36558071, 2022).
idiopathic pulmonary fibrosis (4 papers, 2011 to 2025). Idiopathic pulmonary fibrosis (IPF) is a nonneoplastic pulmonary disease that is characterized by the formation of scar tissue within the lungs in the absence of any known cause. "By degrading the mRNA of transcription factors Gata3 and Egr1, it indirectly suppresses the production of pro-fibrotic cytokines such as IL-5 and IL-13, thereby limiting the progression of idiopathic pulmonary fibrosis (IPF)." (PMID 41154702, 2025).
invasive breast carcinoma (4 papers, 2013 to 2023). A carcinoma that infiltrates the breast parenchyma. "Another example is the loss of Nm23-H1 in invasive breast cancer caused by the downregulation of CTCF and EGR1." (PMID 36120336, 2022). "In conclusion, by applying various bioinformatical approaches we have revealed the decreased expression of pathway elements in the EGF signaling cascade and the decreased expression of the EGR1 gene on the mRNA level in the MDA-MB 231 human invasive breast carcinoma cell line." (PMID 23251236, 2013). "A low level of Egr-1 and CTCF is usually observed in invasive breast cancer." (PMID 37046823, 2023).
keloid (4 papers, 2021 to 2025). An irregularly shaped, elevated mark on the skin caused by deposits of excessive amounts of collagen during wound healing. "During keloid formation, EGR1 responds to TGF-β and promotes ROS production by activating NADPH oxidase 4 (NOX4)." (PMID 38943627, 2024). "It has been shown that miR-203 overexpression led to a significantdecrease of proliferation, invasion in keloid fibroblasts by suppressing EGR1 andFGF2, which implies the potential role of miR-203 in preventing and treating keloids." (PMID 33999095, 2021). "Moreover, transforming growth factor beta 1 (TGF-β1) enhances the expression of early growth response factor-1 (EGR1) in keloids by modulating the small mother against decapentaplegic (SMAD) pathway, thereby promoting the fibrotic phenotype of keloid fibroblasts." (PMID 38671903, 2024).
kidney cancer (4 papers, 2020 to 2023). Primary or metastatic malignant neoplasm involving the kidney. "On the other hand, as overexpression of MITF/TFE family members is responsible for several types of cancer, including kidney cancer, it would be worthwhile to study the contribution of EGR1 to these cancers in vivo." (PMID 36888606, 2023). "Further comparative analysis of gene expression differences between these two subgroups in kidney cancer and normal kidney tissues yielded 2,534 DEGs in NK(EGR1), of which 1,306 were significantly upregulated and 9 were significantly downregulated." (PMID 36046723, 2022). "The acetylation process determines increased levels of EGR1 protein, which can strongly stimulate the expression of genes involved in cell growth and survival, playing a crucial role in prostate and kidney cancers." (PMID 33425921, 2020). "In contrast, in prostate and kidney cancers, EGR1 promotes tumor growth." (PMID 33425921, 2020). "Gene set enrichment analysis revealed that NK(EGR1) and NK(CAPG) were closely related to tumour metastasis, as shown by kidney cancer metastasis to Hodgkin lymphoma, T-cell leukaemia, and Ki-1+ anaplastic large cell lymphoma." (PMID 36046723, 2022). "Compared to that in the normal kidney cells, the NK(EGR1) and NK(CAPG) subpopulations were abnormally elevated in ccRCC and could mediate ccRCC metastasis, such as Hodgkin's lymphoma, T-cell leukaemia, and Ki-1+ anaplastic large cell lymphoma development in kidney cancer." (PMID 36046723, 2022).
latent infection (4 papers, 2013 to 2020). "We identified functional EGR1 binding sites upstream of the UL138 CMV latency gene and EGR1 stimulated UL138 expression to reinforce the latent infection." (PMID 31725811, 2019). "To determine how EGR1 is regulated during CMV latent infection, we analyzed EGR1 mRNA expression in TB40/E-infected CD34+ HPCs derived from two donors at 2 and 6 dpi by RNA sequencing." (PMID 31725811, 2019). "Since HCMV latent infection of CD34+ HPCs results in decreased myeloid colony formation, and expression of EGR-1 is a major determinant in the proliferative capacity of progenitor cells, we examined the direct effects of miR-US22 on myelopoiesis." (PMID 31725809, 2019). "The effects of Egr-1 on HSV-1 gene expression during acute and latent infections are controversial." (PMID 25264522, 2013).
lymph node metastasis (4 papers, 2015 to 2024). "In multivariable analysis, lymph node metastasis was the significant factor associated with EGR1 expression." (PMID 33477921, 2021). "Decreased EGR1 was associated with FIGO stage, lymph node metastasis, and lymphatic metastatic progression." (PMID 39044249, 2024). "In present study, EGR1 was highly expressed in HC samples and correlated significantly with lymph node metastasis, implicating the pro-tumorigenic role of EGR1 in HC." (PMID 25971332, 2015).
migraine (4 papers, 2019 to 2025). "As our previously published data, state, NTG‐induced migraine mice exhibited significantly increased neuronal activities in the somatosensory cortex by recording EGR1 expression." (PMID 41194575, 2025). "Among validated targets describing the migraine disease in the attack-free period, EGR1 (early growth response gene 1) was enlisted, which can regulate multiple aspects of synaptic plasticity." (PMID 36050647, 2022). "Understanding the involvement of Egr-1 in epidemiologically relevant diseases such as migraine and their relationship to CSD may be important for the development of new therapeutic strategies." (PMID 31607855, 2019). "As an important structure involved in the pathogenesis of migraine, TNC showed increased Egr1 expression in this CM mouse model." (PMID 34456674, 2021).
myelodysplastic syndrome (4 papers, 2008 to 2022). A clonal hematopoietic disorder characterized by dysplasia and ineffective hematopoiesis in one or more of the hematopoietic cell lines. "Deletion of the EGR-1 locus is a recurrent genotype in patients with myelodysplastic syndrome and AML." (PMID 25340776, 2014).
ovarian hyperstimulation syndrome (4 papers, 2022 to 2025). A complication of ovulation induction in infertility treatment. "As for the human ovary, EGR1 is implicated in increasing the incidence of ovarian hyperstimulation syndrome, but whether ovarian EGR1 is associated with women’s body weight is unknown." (PMID 40141675, 2025). "Further, the EGR1 increased in granulosa cells and promotes the progression of ovarian hyperstimulation syndrome, which are contrary to the characteristics of ovarian dysfunction (poor ovarian response)." (PMID 39706818, 2024). "Similarly, EGR1 was found to promote ovarian hyperstimulation syndrome through increasing SOX9 expression." (PMID 39665647, 2025).
pancreatic ductal adenocarcinoma (4 papers, 2021 to 2024). An infiltrating adenocarcinoma that arises from the epithelial cells of the pancreas. "The EGR1 expression in normal pancreatic ducts was significantly lower than in pancreatic ductal adenocarcinoma." (PMID 36932397, 2023).